ADAM15 (ADAM metallopeptidase domain 15)
Diseases named in the same sentence as ADAM15 in open-access papers (continued):
Sharing a sentence is not in itself a finding about the gene and the disease.
psoriasis (2 papers, 2013 to 2025). An autoimmune condition characterized by red, well-delineated plaques with silvery scales that are usually on the extensor surfaces and scalp. "Other studies also demonstrated that mice models for psoriasis are ameliorated by interfering angiogenesis by recombinant disintegrin domain of ADAM-15 and pigment epithelium-derived factor, suggesting that angiogenesis is a possible therapeutic target of psoriasis." (PMID 23819059, 2013).
triple-negative breast carcinoma (2 papers, 2019 to 2025). An invasive breast carcinoma which is negative for expression of estrogen receptor (ER), progesterone receptor (PR), and human epidermal growth factor receptor 2 (HER2). "Liu and colleagues recently showed that ADAM15, 10, and 17 regulate mTORC1 and thus autophagy in Triple-negative breast cancer (TNBC) cells." (PMID 41340056, 2025).
abdominal aortic aneurysm (1 paper, 2025). Enlargement and ballooning of the vessel that supplies arterial blood to the abdomen, pelvis and legs. "ADAM15 deficiency exacerbates Ang II-induced aortic remodeling, leading to abdominal aortic aneurysm." (PMID 40643529, 2025). "ADAM15 plays a key role in abdominal aortic aneurysms by regulating VSMC function." (PMID 40643529, 2025).
adenomyosis (1 paper, 2025). The growth of endometrial tissue inside the muscular wall of the uterine corpus. "The novel ADAM15 variant, resulting in premature protein termination, merits functional evaluation to assess its reported impact on intrauterine adhesions, potentially clarifying its involvement in menstrual bleeding and adenomyosis pathogenesis." (PMID 41374450, 2025).
aortic aneurysm (1 paper, 2024). A ruptured aneurysm located in the wall of the proximal portion of the descending aorta proceeding from the arch of the aorta. "Similarly, a previous study documented that Ang II caused a significant increase in ADAM15 protein levels in the abdominal aorta, which could be an important compensatory mechanism that limits aortic aneurysm formation, whereas mice lacking ADAM15 developed aortic aneurysm." (PMID 38916960, 2024).
cardiomyopathies (1 paper, 2020). "Some of these genes, including PTH1R, S100A4 and ADAM15, have been reported to be differentially expressed in DCM or other types of cardiomyopathies." (PMID 31948008, 2020).
chondrosarcoma (1 paper, 2022). A malignant cartilaginous matrix-producing mesenchymal neoplasm arising from the bone and soft tissue. "In conclusion, two separate proteomic methods showed that knockdown of ADAM15 led to minimal alterations in the secretome of chondrosarcoma-like cells." (PMID 35736286, 2022).
COVID-19 (1 paper, 2025). A disease caused by infection with severe acute respiratory syndrome coronavirus 2. "Among them, HLA-C, TCF19, and ADAM15 were shared by PrCa and the two COVID-19 severity phenotypes, while CCHCR1 was shared by PrCa and all three COVID-19 phenotypes." (PMID 41210689, 2025).
Crohn disease (1 paper, 2015). A gastrointestinal disorder characterized by chronic inflammation involving all layers of the intestinal wall, noncaseating granulomas affecting the intestinal wall and regional lymph nodes, and transmural fibrosis. "The other strongest signal we observe links monocyte ADAM15 expression and Crohn's disease risk in the 1q22 region." (PMID 25743184, 2015). "ADAM15 is a metalloprotease, a member of the ADAM (a disintegrin and metalloproteinase) protein family that includes ADAM30, an existing candidate gene for Crohn's disease." (PMID 25743184, 2015).
emphysema (1 paper, 2013). "Another of these genes, ADAM15, which encodes one of the disintegrin and metalloproteinase domain-containing proteins, has been shown to be protective against emphysema as ADAM15−/− mice develop more severe emphysema in response to cigarette smoke." (PMID 24380442, 2013).
gastric cancer (1 paper, 2013). A primary or metastatic malignant neoplasm involving the stomach. "In gastric cancer the expression of ADAM10, ADAM15, ADAM17 and ADAM 20 transcripts is markedly increased." (PMID 25437333, 2013).
glaucoma (1 paper, 2024). Increased pressure in the eyeball due to obstruction of the outflow of aqueous humor. "However, ADAM15 was shown to be a binding partner and target for the podosomal-adaptor protein SH3PXD2B that is mutated in the nee mouse model of glaucoma." (PMID 38394161, 2024).
heart failure (1 paper, 2020). Inability of the heart to pump blood at an adequate rate to meet tissue metabolic requirements. "However, ADAM15 was downregulated in our study, suggesting a complicated pathophysiological role of ADAM15 in heart failure." (PMID 31948008, 2020).
Infertility (1 paper, 2022). "It has been suggested that MAP4K4 affects SH3PXD2A-binding enzymes ADAM12, ADAM15, and ADAM19, which has been shown to be associated with infertility in mutant mouse models." (PMID 36497065, 2022).
lung adenocarcinoma (1 paper, 2022). A carcinoma that arises from the lung and is characterized by the presence of malignant glandular epithelial cells. "A previous study reported the co-expression of ADAM15 and αVβ3 in lung adenocarcinoma, therefore, we examined whether integrin signalling is involved in the ADAM15-induced EGFR signalling pathway." (PMID 35597804, 2022).
lymph node metastasis (1 paper, 2025). "The investigators reported that ADAM15 expression was significantly associated with lymph node metastasis; however, no statistical correlations were observed between ADAM15 expression and the patients’ age, gender, histologic types, tumor differentiation stages, or TNM stages." (PMID 40725774, 2025).
metastatic prostate carcinoma (1 paper, 2016). A carcinoma that arises from the prostate gland and has spread to other anatomic sites. "We also discovered that ADAM15 expression in metastatic prostate cancer correlated with elevated levels of sE-cad found in the serum of these patients and demonstrated that ADAM15 did indeed cleave E-cadherin and N-cadherin in tumor cells." (PMID 26930657, 2016).
prostate adenocarcinoma (1 paper, 2025). "In this regard, the involvement of ADAM15 in cancer progression and metastasis processes has been reported for colorectal, breast, bladder and prostate adenocarcinomas." (PMID 41039222, 2025). "ADAM15 expression is frequently dysregulated in many types of cancer in comparison with the respective normal tissues, and a functional involvement of ADAM15 in cancer progression and metastasis has been proposed for colorectal, breast, bladder, and prostate adenocarcinomas." (PMID 41039222, 2025).
pulmonary fibrosis (1 paper, 2025). Chronic progressive interstitial lung disorder characterized by the replacement of the lung tissue by connective tissue, leading to progressive dyspnea, respiratory failure, or right heart failure. "Increasing evidence suggests that Src family kinases (SFKs), including SRC and HCK, which are strongly correlated with ADAM15, are involved in the pathogenesis of pulmonary fibrosis." (PMID 39824903, 2025).
rectal cancer (1 paper, 2025). A primary or metastatic malignant neoplasm that affects the rectum. "However, the authors assessed ADAM15 expression in colon and rectal cancer tissues using the Gene Expression Profiling Interactive Analysis 2 (GEPIA2 2019) tool and data available in The Cancer Genome Atlas (TCGA)." (PMID 40725774, 2025).
Renal insufficiency (1 paper, 2025). A reduction in the level of performance of the kidneys in areas of function comprising the concentration of urine, removal of wastes, the maintenance of electrolyte balance, homeostasis of blood pressure, and calcium metabolism. "Finally, for Renal insufficiency, 3,041 genes and 363 related proteins were identified, with 72 gene-protein overlapping targets such as ADAM15, CD86, and AARSD1." (PMID 41340073, 2025).
sarcoidosis (1 paper, 2025). Sarcoidosis is a multisystemic disorder of unknown cause characterized by the formation of immune granulomas in involved organs. "Through rigorous sensitivity analyses, we ultimately identified three proteins as priority candidates with significant druggable potential: CDH15 for ILD excluding IPF, ADAM15 for both IPF and ILD, and LTBR for sarcoidosis." (PMID 39824903, 2025).
Sepsis (1 paper, 2014). Sepsis is defined as life-threatening organ dysfunction caused by a dysregulated host response to infection. "Since increased ADAM15 expression contributes to endothelial barrier dysfunction during sepsis and inflammation, we sought to explore the therapeutic potential of suppressing ADAM15 expression in treating edematous injury." (PMID 25333931, 2014).
transitional cell carcinoma (1 paper, 2016). A malignant neoplasm arising from the transitional epithelium, usually affecting the urinary bladder, ureter, or renal pelvis. "Utilizing the transitional cell carcinoma lines UM-UC-9 and UM-UC-6, we assessed ADAM15 protein level by immunoblot analysis using a cytoplasmic-specific antibody against ADAM15." (PMID 26930657, 2016).
transitional cell carcinoma of the bladder (1 paper, 2016). "The in vivo significance of reduced ADAM15 activity was analyzed in xenograft models of transitional cell carcinoma of the bladder." (PMID 26930657, 2016).
Type 2 diabetes (1 paper, 2007). "In vitro, Type 2 diabetes LDL promoted the expression of the MMP-1, MMP-9, ADAM28, ADAM17 and ADAM15 genes compared to control LDL." (PMID 17714581, 2007).
cancer (38 papers, 2007 to 2025). A tumor composed of atypical neoplastic, often pleomorphic cells that invade other tissues. "In a recent study, ADAM15 was linked to aggrephagy, an autophagy-related process that regulates cancer progression." (PMID 41340056, 2025). "Some investigations reported that the upregulation of ADAM15 has been linked to worse survival in cancer patients and a tumor-promoting function both in vitro and in murine cancer models." (PMID 40725774, 2025). "It has been reported that ADAM15 is upregulated in many malignant tumours, and the high expression of ADAM15 is associated with the progression of tumours." (PMID 35597804, 2022). "This is of special relevance because aberrant ADAM15 expression has been associated with human cancer and the alternative splicing of ADAM15 is mis-regulated in cancer cells." (PMID 34496885, 2021). "Altered ADAM15 expression has been associated with human diseases, including cancers, cardiac disease, atherosclerosis, and arthritis." (PMID 17937806, 2007). "This regulation appears to be disturbed in cancer cells which show aberrant ADAM15 variant patterns." (PMID 17937806, 2007). "In cancer, ADAM15 has been implicated in tumor growth, angiogenesis and metastasis." (PMID 41039222, 2025). "Indeed ADAM15 has recently been identified in a large genome-wide association study of over 60,000 cancers in multiple sites as a locus with pleiotropic associations with breast and lung cancer." (PMID 31467400, 2019). "Aberrant ADAM15 expression has been associated with human cancer and other disorders." (PMID 17937806, 2007). "In cancers, ADAM15 has been implicated in tumor growth, angiogenesis, and metastasis." (PMID 17937806, 2007). "ADAM15 is associated with diverse biological functions in cancer progression and metastasis, such as neovascularization, tissue-remodeling, reduction in cell-cell adhesions and the release of various cytokines and growth factors that may promote tumor growth and survival." (PMID 26930657, 2016). "The ADAM15-dependent regulation of cell migration also has important repercussions in cancer development and progression." (PMID 41039222, 2025). "Some clinical investigation reveals a novel mechanism of ADAM15 in promoting cancer cell invasion through directly targeting MMP9." (PMID 40725774, 2025). "It has been shown that, in addition to transcriptional regulation of ADAM15 expression, alternative splicing of ADAM15 transcripts is also dysregulated in human cancer cells." (PMID 41039222, 2025). "Cancer cell-derived ADAM15 promotes the progression of this malignancy by modulating the tumor microenvironment." (PMID 40725774, 2025). "Among ADAMs that exhibit a functional protease domain, ADAM15 is proved to be upregulated in the most common cancer types, including CRC." (PMID 40725774, 2025). "In most cases however, ADAM15 involvement in cancer progression seems to depend fundamentally on its metalloproteinase activity rather than on its RGD-based adhesive properties." (PMID 41039222, 2025). "Enhanced ADAM15 expression has been described for many cancer types and correlates with poor prognosis and metastasis formation." (PMID 41340056, 2025). "Of note, ADAM15 expression is frequently dysregulated (either overexpressed or downmodulated) in many types of cancer relative to the respective benign tissue counterparts." (PMID 41039222, 2025). "ADAM15 is catalytically active and is normally expressed in primitive embryonic development, however, it is improperly expressed in diverse cancers, such as lung, prostate, and breast." (PMID 38317965, 2024). "Disintegrin-metalloproteinase 15(ADAM15), a member of disintegrin metalloproteinases (ADAMs), plays important roles in various cancer types." (PMID 35597804, 2022). "It has been shown that 63% of CRC cells demonstrate reduced expression of ADAM15 in cancer cells, which has been evaluated at the mRNA level." (PMID 35565436, 2022).
cancer (continued). "For example, even though one study suggested that ADAM15 is decreased in CRC, there are several other studies that found there is an increase in expression of ADAM15 in several types of cancer." (PMID 34502094, 2021). "Recent studies have also suggested that ADAM15 is overexpressed in several types of cancer and is involved in metastatic tumor progression." (PMID 34502094, 2021). "Several members of ADAMs, such as ADAM10, ADAM12, and ADAM15, have been reported to be overexpressed in human cancers." (PMID 32637415, 2020). "These associations provide new insights into the mechanisms by which ADAM15 contributes to progression of breast and other cancers, highlighting in particular the significant differences between the ICD variant forms of ADAM15." (PMID 31467400, 2019). "Several ADAM family members, particularly ADAM9, ADAM10, ADAM12, ADAM15 and ADAM17, have been implicated in cancer formation and progression." (PMID 30081852, 2018). "Our previous work has also demonstrated that ADAM15 can proteolytically process different molecules to modulate cell adhesion and cancer cell metastasis." (PMID 26930657, 2016). "We have previously shown that the alternative splicing of ADAM15 transcripts is mis-regulated in cancer cells." (PMID 17937806, 2007). "Knowledge of the ADAM15 gene structure and transcriptional control elements are important prerequisites for better understanding of its mis-regulation in cancers and other diseases as well as for the elucidation of its physiological role." (PMID 17937806, 2007). "Modified alternative exon usage regulation of ADAM15 may be useful for cancer diagnosis since diverse combinations of its isoforms (derived from three alternative exons) can be easily examined with a PCR protocol." (PMID 38317965, 2024). "It is suggested that the role of ADAM15 in cancer progression is tissue-specific." (PMID 34502094, 2021). "ADAM15 is highly expressed in malignant tumors and is correlated with tumor progression." (PMID 34426560, 2021). "E-cadherin has been shown to be cleaved by ADAM9, ADAM10, and ADAM15 in cancer cells in vitro." (PMID 28260841, 2017). "Interestingly, macrophage- and tumor-derived exosomes containing ADAM15 have a similar effect on cancer cell adhesion and migration via the same mechanism." (PMID 28260841, 2017). "Possible mechanisms for the promotion of cancer progression by ADAM-15 include disrupted cell adhesion, sheddase activity promoting autocrine and paracrine signaling, the breakdown of extracellular matrix and basement membranes, and a role in neovascularization and angiogenesis." (PMID 24317528, 2013). "In addition to the transcriptional regulation of ADAM15 expression, alternative splicing of ADAM15 transcripts has been shown to be mis-regulated in human cancer cells." (PMID 17937806, 2007). "Thus, enhanced HER2/HER3 signaling is a potential mechanism by which ADAM-15 could contribute to cancer progression." (PMID 22069559, 2010). "Therefore, we hypothesized that ADAM15 plays a dual role in the context of various types of cancer." (PMID 35597804, 2022). "Several substrates of ADAM15, including EGFR ligands such as HB-EGF, TGFα, amphiregulin, betacellulin, and other factors including Notch, and cytokines have been identified in cancer cells." (PMID 26930657, 2016). "The overexpression of ADAM8, ADAM9, ADAM10, ADAM12, ADAM15, ADAM17, and ADAM28 are reported from various cancers." (PMID 22272227, 2012). "ADAM15 is proposed to play a dual role in cancer metastasis, not only by leveraging its disintegrin and metalloproteinase domains but also by promoting tumor cell migration and angiogenesis." (PMID 40725774, 2025). "ADAM28 may play a key role in cancer cell proliferation and metastasis, whereas ADAM17 is a target of tumorigenesis, but the role of ADAM15 in cancer biology remains to be elucidated." (PMID 35565436, 2022).
cancer (continued). "The VSV-resistant PC-3 cell line showed reduced matrix metalloprotease activity and metastasis upon ADAM15 suppression, suggesting that this modulation of the inflammatory response by VSV may also hold true in cancer cells." (PMID 35108303, 2022). "Identification of ADAM15 isoform-dependent shed substrates using approaches such as TMT-MS-TAILS33,34, will have significant implications for cancer patients, as well as for advancing our understanding of the role of ADAM15 splicing for cancer biology and progression." (PMID 31467400, 2019). "ADAM-15, with known zymogen, secretase, and disintegrin activities, is a catalytically active member of the ADAM family normally expressed in early embryonic development and aberrantly expressed in various cancers, including breast, prostate and lung." (PMID 24317528, 2013). "ADAMs shown to play a role in cancer include ADAM9, ADAM10, ADAM12, ADAM15 and ADAM17." (PMID 21906355, 2011). "However, according to our knowledge, this study is the first to assess serum ADAM15 concentrations in CRC patients in comparison to classical tumor markers—carcinoembryonic antigen (CEA) and cancer antigen 19-9 (CA19-9)—and a marker of the inflammatory process, C-reactive protein (CRP)." (PMID 40725774, 2025). "Moreover, soluble E-cadherin in serum serves as cancer prognostic marker and the soluble fragment in urine corresponds to the 80 kDa ectodermal fragment of the protein, which can be cleaved by several proteases including plasmin, MMP3, MMP7, ADAM10, and ADAM-15." (PMID 32121033, 2020).